CCL2 (C-C motif chemokine ligand 2)
Diseases named in the same sentence as CCL2 in open-access papers (continued):
Sharing a sentence is not in itself a finding about the gene and the disease.
tumor (continued). "Additionally, trabectedin inhibits the production of specific inflammatory mediators in macrophages, such as IL-6 and C-C motif ligand 2 (CCL2), which likely contributes to the depletion of the TAM pool in the tumor microenvironment." (PMID 40918451, 2025). "Overall, key cell subsets including OMD+ fibroblasts, CCL2+ macrophages, and S100A2+ tumor cells might collectively contribute to a pro-tumor microenvironment conducive to LNM in PDAC." (PMID 40092486, 2025). "Chemokines such as CCL2, CCL5, and CXCL12 are known to recruit myeloid‐derived suppressor cells (MDSCs) to the tumor microenvironment, where they suppress T‐cell responses and promote tumor growth." (PMID 40145607, 2025). "Moreover, neutrophil-derived ROS and NETs can further polarize macrophages toward a tumor-promoting state, while TAMs modulate neutrophil recruitment and survival via chemokines such as CXCL8 and CCL2." (PMID 40868256, 2025). "This, in turn, promotes TAM polarization and may drive tumor progression by increasing the secretion of PDGF-A, VEGF-A, and CCL2." (PMID 39905317, 2025). "It has been demonstrated that tumor cells release inflammatory cytokines (IL-6, IL-1, TNF-α), chemokines (CCL2, CCL5, CCL15, CCL26), and growth factors (TGFβ), which ultimately recruit BMDCs such as myeloid-derived suppressor cells (MDSCs) and create a favorable niche for tumor development." (PMID 41383620, 2025). "Upon tumor challenge, only irradiated mice lacking Ccl2-expressing IMs showed reduced tumor burden, while busulfan-treated mice with preserved Ccl2-expressing IMs developed larger tumors." (PMID 40630529, 2025). "Inhibition of the CCL2/CCR2 axis, critical for inflammatory cell recruitment, may also reduce tumor-induced immunosuppression and activate anti-tumor immunity." (PMID 41011273, 2025). "They secrete CCL2 to recruit myeloid cells, creating a feedback loop where macrophage-secreted IL-6 and oncostatin M activate the JAK/STAT/RP11-355I22.7 axis, promoting tumor growth." (PMID 40016470, 2025). "Additionally, TAMs release pro-inflammatory cytokines (such as TNF-α) and chemokines (CCL2, CXCL8), which promote the expansion and maintenance of CSC populations within the tumor microenvironment." (PMID 40771808, 2025). "Additionally, tumor-secreted VEGF, transforming growth factor β (TGFβ), tumor necrosis factor α (TNFα) and CCL2 can induce lung angiogenesis and trigger local inflammation." (PMID 40370456, 2025). "Tumor-associated macrophages (TAMs), which predominantly exhibit M2-like characteristics, are recruited to and infiltrate tumors in the tumor microenvironment (TME) via chemotactic factors derived from tumor and immune cells, including C-C motif Chemokine Ligand 2 (CCL2)." (PMID 40806751, 2025). "TAMs promote the EMT of tumor cells by secreting various factors, including TGF-β, IL-6, and CCL2." (PMID 40304000, 2025). "In addition, chemokines secreted at necrotic tumor sites by C-C motif chemokine ligand 2 (CCL2) and C-C motif chemokine ligand 5 (CCL5) allow for higher macrophage recruitment and infiltration in tumor tissues." (PMID 40725148, 2025). "Notably, the combination of sh-CMTM6-Exos and RS504383 resulted in the most significant tumor suppression, suggesting a potential additive or synergistic interaction between exosomal CMTM6 and CCL2 signaling in promoting CC progression." (PMID 40761779, 2025). "Apart from CCL2, it is noteworthy that another C motif chemokine ligand, CCL5, also promotes the recruitment of TAMs and contributes to tumor metastasis and recurrence, which can be restricted by the CCL5 receptor antagonist maraviroc and the Raf kinase inhibitory protein." (PMID 39065562, 2024). "An alternative treatment approach may include blockade of CCL2 signaling involved in recruitment of TAMs to the TME which was shown to reduce tumor progression in several experimental tumor models." (PMID 38533720, 2024).
tumor (continued). "Plasma levels of MCP-1 strongly correlate with OS progression and osteolysis, and administration of zoledronic acid directly attenuates OS RANKL/CCL2 production and reduces tumor-induced bone destruction." (PMID 39199574, 2024). "Our trial did not assess tumor microenvironment components, but these potential compensatory changes support further exploration of combined CCL2/CCR2 and angiogenic inhibition." (PMID 38697618, 2024). "Similarly, pharmacologic inhibition of STAT3 or genetic depletion of CCL2 and CCL7 reduced pro-tumor CD45highCD11b+CD68+CD206+ macrophages in CT2A tumors." (PMID 38443336, 2024). "Changes in the expression and secretion profile of inflammatory mediators in CAAs, such as increased secretion of chemokines CCL2, CCL5, IL-6, TNF-α, VEGF, leptin, etc, will further promote the proliferation and invasion of tumor cells and the formation of new blood vessels." (PMID 39544302, 2024). "Chrysotile induced a more profound immune tumor response than crocidolite in Bap1-mutant mice by upregulating CD39/CD73-adenosine and Ccl2/Ccr2 pathways and recruiting more M2 macrophages, which together contributed to an immunosuppressive tumor microenvironment." (PMID 38592450, 2024). "CCL2 siRNA treatment did not significantly affect tumor mass, indicating that the effects of tumoral CCL2 knockdown on lean mass were independent of tumor growth." (PMID 38973385, 2024). "In addition to macrophage colony-stimulating factor (M-CSF) and tumor-derived factors such as chemokines CCL2, CCL3, CCL4, and CCL5, which serve as macrophage chemoattractants, CCL2 is extensively expressed in various human tumors." (PMID 38840908, 2024). "This may result from the underexpression of CCL2 and CCR2, responsible for monocyte recruitment to tumor sites, and the reduced levels of IL4 and IL13, genes known to promote monocyte polarization into M2 macrophages." (PMID 38733987, 2024). "Moreover, the secretion of tumor chemokines such as CXCL10, CCL2, CCL3, and adhesion molecules such as ICAM-1 and VAP-1 by LSECs in HCC promotes leukocytes’ recruitment and the accumulation of other immunosuppressive cells like TAMs and Tregs." (PMID 38730724, 2024). "Additionally, several immunosuppressive mediators, including CCL2, CCL5, CSF1, and TGFβ, secreted from CICs, are shown to promote macrophage and Treg recruitment into tumor tissue, while suppressing T cell responses, contributing to immune resistance." (PMID 38253555, 2024). "A clinical phase 1 trial targeting the CCL2/CCR2 signaling axis showed positive results, with an objective tumor response occurring in 49% and local tumor control in 97% of patients treated with the CCR2 antagonist PF-04136309 in combination with FOLFIRINOX chemotherapy." (PMID 40458305, 2024). "Despite being well-tolerated, carlumab did not effectively block the CCL2/CCR2 axis or demonstrate anti-tumor activity as a single agent in mCRPC." (PMID 39518123, 2024). "While IL-1α KO tumors contained lower levels of chemokines, such as CCL2 and CXCL1/2/3, known to attract MDSCs into the tumor, they showed higher expression of CCL5, CXCL9/10, which could attract T lymphocytes and NK cells." (PMID 38612760, 2024). "TRAIL-triggered CCL2 secretion from TRAIL-resistant cancer cells can drive monocyte polarization to MDSCs and M2-like macrophages, which promotes accumulation of tumor-supportive immune cells in the tumor microenvironment." (PMID 39056714, 2024). "This suggests that the CCR4 receptor may be the significant molecule mediating Treg migration to the tumor site in response to CCL2 and possibly other CCR4 ligands secreted in the tumor environment." (PMID 39046599, 2024). "Moreover, CCX872-B, another CCR2 antagonist, disrupts the CCL2/CCR2 signaling pathway, reducing monocyte recruitment and subsequent tumor-promoting inflammation." (PMID 39076996, 2024).
tumor (continued). "Besides cytokines, TAMs secrete chemokines like CCL2, which attract immunosuppressive cells such as MDSCs and Tregs to the TME, thereby augmenting tumor immunosuppression." (PMID 38713256, 2024). "Moreover, tumor cells also secrete angiopoietin-like 4 (ANGPTL4) and C-C-chemokine ligand 2 (CCL2), which antagonize endothelial cell tight junctions, promoting tumor cells extravasation." (PMID 39035739, 2024). "Additionally, a differential expression of the cytokine genes CCL2, CCL20, TGFB1, and TGFB2; the transcription factor gene IRF4; and the receptor genes CCR2, IL10RB, TGFBR1, and TGFBR2 was identified in tumor tissue and vestibular nerve tissue." (PMID 39272860, 2024). "In addition, other targets that inhibit recruitment CCL2 and CCL5 have good tolerance but poor anti-tumor activity in clinical trials." (PMID 38787372, 2024). "In most cancers, macrophages are enriched by infiltrating MDMs that are recruited from the periphery in response to signals from the TME (e.g., CCL2, CCL9, CSF-1, VEGF, and TGF-b), and their in situ phenotype is shaped by a combination of organ- and tumor-derived signals." (PMID 39068459, 2024). "While CCL2 expression by tumour cells can stimulate nontumour cells via a paracrine mechanism, CCL2 can also activate tumour cells via an autocrine mechanism." (PMID 38809883, 2024). "Cytokines, including CCL2, CCL5, CCL18, TGFB1, and GDF15, are produced by tumor cells and attract immune cells, such as macrophages and lymphocytes, from the blood and bone marrow into the tumor microenvironment." (PMID 39272860, 2024). "The A3250 IBC cells and human IBC tumors highly expressed CCL2 compared to non-IBCs, and CCL2 knockdown (KD) markedly reduced A3250 tumor growth and lung metastasis." (PMID 38786066, 2024). "The CCR2 ligand CCL2 has been observed to be upregulated in EBV lymphoma lines; therefore, higher CCR2 expression indicates an increased capacity for peptide VST to migrate to and infiltrate within the tumor microenvironment." (PMID 39011042, 2024). "CCL2 is highly expressed in a variety of malignant tumor cells, but its receptors (CCR2b and CCR4) are only slightly expressed on the surface of activated CAR-T cells that target tumor antigens." (PMID 39023820, 2024). "Interestingly, immunomodulatory proteins such as CSF-1, CCL2, FTH, FTL, and TGF-β chemokines have been identified in tumor exosomes." (PMID 39008536, 2024). "Independent of the tumor volume, the concentration of CCL2 in the CSF of the patients was lower than in the CSF of the control group." (PMID 39272860, 2024). "Mechanistically, early radiation-induced apoptosis promoted the proliferation of CD8 + T cells, while increased chemokine CCL2 levels from localized and distant tumor sites facilitated CAR-T and endogenous T cell infiltration, leading to systemic tumor suppression." (PMID 39578426, 2024). "Intriguingly, CCL2, a potent chemokine known to attract monocytes and various immune cell populations, has been identified as a pivotal chemotactic factor involved in the recruitment of TAM and MDSC into tumor tissues." (PMID 38952044, 2024). "MDSCs express several chemokine receptors such as CCR2, CXCR2, CXCR4, and CXCR5, while liver tumor cells or malignant hepatocytes express chemokines such as CCL2, CCL5, CXCL1, CXCL5, and CXCL12, and the chemokine/its receptor axis mediates MDSC infiltration in the tumor microenvironment." (PMID 38397901, 2024). "Furthermore, certain chemokine family members such as CCL1, CCL2, and CCL5, which are highly expressed by CSCs in different cancer types, stimulate the infiltration of T-reg cells into the tumor microenvironment." (PMID 39671359, 2024). "IHC was used to assess CCL2 expression in both TLS regions and adjacent tumor areas." (PMID 39595209, 2024).
tumor (continued). "We then performed ELISA to detect the secretion level of CCL2 in serum from mouse xenograft models bearing MELK knockdown tumors or the corresponding control tumors, and a reduced concentration of CCL2 was detected in MELK knockdown tumor-bearing mice." (PMID 38970074, 2024). "Studies have found that CCL2 expression correlates with higher tumor stage, with muscle-invasive BCa showing greater CCL2 expression than non-muscle-invasive BCa." (PMID 39409924, 2024). "Indeed, in response to antibody-coated tumor cells, NK cells produce IL-8, MDC, MIP-1 and CCL2, which are chemokines involved in T cells recruitment." (PMID 39179536, 2024). "Furthermore, CXCL2, CXCL12, CCL2, and CXCL8 in humans have each been observed to regulate G-MDSC recruitment to the tumor microenvironment." (PMID 37988164, 2024). "CCL2 protein expression was not correlated with gender (p = 0.076) but was significantly correlated with age (p < 0.05), histology type (p < 0.005), tumour size (p < 0.01) and TNM stage (p < 0.05), as determined by chi‐squared test." (PMID 37850256, 2024). "Thus, observed decreases in CCL2, CCL7 and CCL12 suggest a reduction in factors that promote pro-tumor, M2-like macrophage differentiation and infiltration." (PMID 38575562, 2024). "Interestingly, while TWEAK secretion is not high in PDAC tumor cells, macrophages can respond to tumor cell-secreted CCL2, activate and secrete CCL5, and significantly upregulate TWEAK expression and secretion in tumor cells via the TRAF6/NF-κB pathway." (PMID 38982491, 2024). "For example, cancer cells produce CCL2 to recruit inflammatory CC chemokine receptor 2(CCR2) monocytes from blood to metastatic sites, where they differentiate into related macrophages and promote tumor cell extravasation under the influence of VEGF." (PMID 38840908, 2024). "Injection of oxPAPC in vivo significantly upregulated the percentage of MDSCs in tumour microenvironment (TME) of wild‐type LL2 tumour‐bearing mice, but not CCL2−/− mice and LTB4R−/− mice." (PMID 37905494, 2024). "The CCL2/CCR2 signaling axis also recruits various immune cells to form an immunosuppressive TME in both the early and late stages of metastasis, which allows tumor cells to evade immune surveillance." (PMID 38468260, 2024). "As a result, it showed that neither IFI35 ablation in WT tumor cells nor CCL2 rescue in Ifi35ko tumor cells affected the expression of PD-L1." (PMID 38216673, 2024). "Chemokines like CCL2 and CCL5 are essential for recruiting regulatory T cells, inflammatory monocytes, and macrophages, creating an immunosuppressive environment in the TME that supports tumor growth and worsens patient prognosis." (PMID 38791448, 2024). "Chemokines CCL2 and CCL5 are produced in various cancers and server as pivotal factors in the recruitment of mononuclear/macrophage cells to the tumor microenvironment, especially in tumor metastasis." (PMID 39606239, 2024). "The chemokines CCL2 and CCL3 recruit pro-tumor macrophages into the TME." (PMID 38742117, 2024). "Here, we investigated the role of CCL2 signaling on SMW in tumor and non-tumor contexts." (PMID 38973385, 2024). "Interestingly, we observed a significant reduction in the number of macrophages and MDSC in the presence of the CCL2 antibody, suggesting that PRPS2‐mediated regulation of CCL2 in tumor cells plays a crucial role in the chemotaxis of TAMs and MDSC." (PMID 38952044, 2024). "Cancer cells can produce CCL2 and other chemokines in response to TNF stimulation, which enhances their metastatic potential and recruit leukocytes with pro-metastatic effects to the tumor microenvironment." (PMID 39206193, 2024). "Moreover, it is possible that CCL2, CCL5, CCL18, TGFB1, and GDF15 are also produced by cells other than the VS tumor cells." (PMID 39272860, 2024).
tumor (continued). "We also analyzed the correlation between the expression of CCL2 in tumor cells and macrophage infiltration in GSE125449 cohort and found that there was a positive correlation between the expression of CCL2 in KRT18 + tumor cells and CD68 + macrophages infiltration." (PMID 38970074, 2024). "Targeting the CCL2/CCR2 has shown some promise in preclinical murine models of HCC, with the CCR2 antagonists, RDC018 and 747, exhibiting good efficacy in an orthotopic liver tumour model, significantly restricting tumour growth and metastasis." (PMID 39684877, 2024). "In cancer patients, NK cells can recognize and eliminate tumor cells by releasing cytolytic molecules perforin and granzymes, as well as modulate the adaptive anti-tumor immune response by producing chemokines and cytokines such as IFN-γ, TNF-α, IL-8, IL-10, and CCL2." (PMID 38254110, 2024). "Certain chemokines (such as CXCL9 and CXCL10) can promote anti-tumor immune responses, while others (like CCL2 and CXCL12) may facilitate tumor progression." (PMID 39030403, 2024). "Notably, IL-6 can elevate the levels of EIF4A3 and CCL2 in tumor cells via activation of the JAK2/STAT3 pathway, further facilitating tumor cSERPINE2 biogenesis and inducing TAMs recruitment." (PMID 38397395, 2024). "The increased secretion of CCL2 and CXCL2 may have accounted for the enhanced migration of MDSCs in the peritoneal cavity of tumor-bearing METTL3-cKO mice." (PMID 37932814, 2023). "CCL2 KO MSCs inhibited the migration of the monocyte/macrophage but not the proliferation of tumor cells in vitro." (PMID 36672395, 2023). "A gene set enrichment analysis of genes that were significantly differentially expressed within each tumor group revealed enriched tissue remodeling and matrix organization in TNC/CCL2 high tumors versus TNC/CLL2 low tumors, along with altered innate and adaptive immune processes." (PMID 37176074, 2023). "The CCL2/CCR2 signaling pathway contributes to tumor-promoting myelogenesis by enhancing splenic EMH and substantially promotes the migration and accumulation of MDSCs in tumor tissues." (PMID 37415162, 2023). "Furthermore, the highly expressed DEGs of fibroblasts in LNM included immune-related genes (CCL21, CCL19, CCL2, and MYC), metabolism-related genes (STEAP4, FABP4, DPT, and APOE), and genes related to tumor proliferation and progression (RGS, CCN, and MYC)." (PMID 37221625, 2023). "Also, CCL2/CCR2 assists in the tumor-promoting inflammation and recruitment of the TAMs in the tumor sites." (PMID 38017494, 2023). "These genes include markers of alternative macrophage polarization (Arg1, Cd163), monocyte chemoattractant Ccl6, and ligands for CCR2 (Ccl2, Ccl7, Ccl12) and CCR5/1 (Ccl3, CCl4, Ccl9) suggesting that F4/80+ cells in these tumours represent an increase in TAM2‐like myeloid cells." (PMID 35924447, 2023). "Furthermore, many other different molecules produced by tumor cells or by cells of the TME can induce MC chemotaxis, including CCL2, CCL5, CCL11, CCL15, CXCL12, VEGF, FGF2, osteopontin, and lipid mediators." (PMID 37376140, 2023). "Therefore, mRNA expressions of chemokines CCL2, CCL17 and CCL22, as well as IL-6, IL-18, TNF-α and IFN-γ, in tumor tissues and H22 cells were detected by RT-qPCR." (PMID 36674931, 2023). "The chemokine CCL2, which is derived from the TME, is known to plays a crucial role in the migration and recruitment of blood-derived monocytes that contribute to the immunosuppressive TME and tumor progression." (PMID 37598273, 2023). "By contrast, CXCL1, CXCL2, CCL2 and TGFB2 with defined pro-tumorigenic roles are more highly expressed by EA1 tumor cells at baseline and may antagonize anti-tumorigenic effects of CD8+ T cells that do infiltrate this model." (PMID 36739466, 2023). "Testing in either cell culture or the tumor xenografts showed that ACKR1 expression could prevent the spike of CCL2 and CXCL8 released into the growth media or tumor microenvironment." (PMID 37006247, 2023).